ANKRD19P (ankyrin repeat domain 19, pseudogene)
Synonyms: FLJ36178; formerly ANKRD19
Gene: Transcribed unprocessed pseudogene on chromosome 9 (92,809,665 to 92,826,578, forward strand). Ensembl gene ENSG00000187984.
Diseases named in the same sentence as ANKRD19P in open-access papers:
ANKRD19P is named in the same sentence as 2 diseases in open-access papers, as found by Europe PMC text mining. Sharing a sentence is not in itself a finding about the gene and the disease.
ANKRD19P shares sentences with these, for which no sentence is quoted: cognitive decline (1 paper); dementia (1).